CD3E (CD3 epsilon subunit of T-cell receptor complex)
Diseases named in the same sentence as CD3E in open-access papers (continued):
Sharing a sentence is not in itself a finding about the gene and the disease.
tumor (continued). "The immunocompetent, syngeneic EMT6 tumor model replicated the progenitor behavior in a xenograft model: nearly 100% of EMT6-recruited Lyve-1+ cells expressed CD11b but only 1–3% co-expressed either Ter-119 or CD3e." (PMID 38640116, 2024). "CD19/CD3ε FP T cells were administrated into mice 3 days after tumor inoculation." (PMID 38023726, 2023). "Tumours isolated from mice were stained positive for CD3ε, CD56 and EBER via immunohistochemistry." (PMID 37649020, 2023). "A significant increase in percentages of CD3ε+ T-cells and both T-cell subpopulations as well as NK-T cells was also observed in sham-treated splenectomized mice, indicative for enhanced T-cell-mediated anti-4T1 tumor responses upon splenectomy." (PMID 37928528, 2023). "Based on the specific locations of the GUCY2C and CD3ε epitopes and the rigid arrangement of the diabody binding sites, facing opposite from each other, we estimated a distance of about 140 Å between the membranes of the tumor cell and the T-cell." (PMID 37591971, 2023). "Specifically, in the tumor from patient #7, genes involved in T cell activation and signaling such as PTPRC (which encodes CD45), LCP2, FYB, CD3E, and LCK, and in genes involved in immune response and interferon signaling such as STAT1, OAS2, and HLA were downregulated." (PMID 37620318, 2023). "However, the relative efficacy of CD3ε FP T cells compared to lentiviral CAR‐T cells needs to be further evaluated across different tumor models and tumor targets." (PMID 38023726, 2023). "Both genotypes responded to MEK + CDK4/6 inhibition; however, ΔS tumors uniquely showed induction of necrosis detected by ultrasound, which was preceded by an early reduction in tumor size, increase in CD3e+ T-cell infiltration and engagement of an antitumor myeloid cell phenotype." (PMID 36344707, 2022). "Interestingly, we found that T-cell clusters were present at high levels in immune cells, and the presence of infiltrating T cells in tumor tissues was confirmed using immunohistochemistry (IHC) with CD3E, CD4 and CD8 antibodies." (PMID 36466840, 2022). "With the adjustment based on purity, the correlation analysis in STAD revealed that DDR1 was closely linked to most of immune markers in various TIICs, such as CD3E of general T cells, CD86 of monocytes, CCL2 of tumor-associated macrophages (TAMs), and CCR7 of neutrophils." (PMID 35935941, 2022). "Therefore, B2-OKT3 BiTE can target MICA on tumor cells and CD3ε on T cells through the tandem scFv BiTE format, which specifically induces T cells to kill tumor cells." (PMID 35401191, 2022). "However, anti-PD-L1 treatment resulted in upregulation or downregulation of numerous genes in CD45+ tumor-infiltrating immune cells in TCh3 tumors, including Cd3d, Cd3e, Cd3g, Cd8a, Cd8b1, Nkg7, Ccl5, Ets1, Icos, Cxcr6, Pdcd1, Lag3, Prf1, and Gzmb (right)." (PMID 35366939, 2022). "This study identified tumor microenvironment-related genes, including monokine induced by gamma interferon (MIG or CXCL9), E26 transformation-specific variant 7 (ETV7), guanylate binding protein 4 (GBP4), and CD3 epsilon chain (CD3E)." (PMID 34054929, 2021). "Bispecific T-cell engagers (bsTCEs) tackle this challenge by redirecting non-tumor specific T cells through the binding to CD3ε of T-cell receptors (TCRs) by one arm and to tumor cells via the binding to tumor-associated antigen (TAA) by the other arm." (PMID 33808165, 2021). "Evaluating the ratio of differential tumor purity and CD3E expression levels may provide novel insights into the complex structure of the LGG microenvironment and targeted drug development." (PMID 34557404, 2021). "Therefore, we suspect that in the development of LGG, the up-regulation of CD3E promotes the decline of tumor purity." (PMID 34557404, 2021).
tumor (continued). "Notably, the T cells activated by blinatumomab can induce serial killing of targeted tumor cells since the affinity of blinatumomab for CD3ε subunit (10−7 M) is much lower than that for CD19 (10−9 M) which increases the mobility of bound T cells." (PMID 34117317, 2021). "CD3E, novel membrane immune biomarker deeply affecting tumor purity, may help to evaluate the prognosis and develop individual immunotherapy strategies for LGG patients." (PMID 34557404, 2021). "This may be because CD3E, as a core gene, regulates the tumor immune microenvironment in a completely different manner than that of extracranial tumors." (PMID 34557404, 2021). "Tumour sections were fluorescently labelled with the T-cell marker CD3ε and nuclear stain DAPI." (PMID 34168276, 2021). "Based on the known annotation of marker genes from the literature, we grouped cells of nine clusters into four cell types: GNP-like tumor cells (expressing Math1 and Grin2b), microglia (expressing Aif1 and Cd68), T cells (expressing Cd3d and Cd3e), and endothelial cells (expressing Cldn5 and Cdh5)." (PMID 34210306, 2021). "Notably, highly proliferating Ki67-positive tumor cells and CD3e-positive lymphocytes were found across all subtypes, with no clear difference among subtypes." (PMID 34031426, 2021). "In addition, we also found that the CD3D, CD3E and LCK expression was significantly negatively related to tumor purity while positively associated with the infiltrating levels of immune cells, such as B cell, CD8 + T cell, and CD4 + T cell." (PMID 33748188, 2021). "However, both AURKA and AURKB expression were significantly inversely correlated with markers for T-cell infiltration of the tumor: CD3E, CD4, CD8A, LCK, PDCD1 and IFNG." (PMID 33123754, 2021). "The tumor tissues express CD3ε, CD43, CD56, and cytotoxic molecules (such as TIA-1 and GB)." (PMID 33816224, 2021). "In follow-up research, we could devote ourselves to exploring the biological malignant function of CD3E and its regulatory mechanism on the tumor immune microenvironment in in vitro cell lines, in vivo animals, and large-scale multicenter LGG patients." (PMID 34557404, 2021). "Evaluating the ratio of different tumor purity and CD3E expression may provide novel insights into the complex structure of the LGG microenvironment and targeted drug development." (PMID 34557404, 2021). "We believe that CD3E may be expressed in T cells in the tumor microenvironment and is a promising therapeutic target." (PMID 34124265, 2021). "Bispecific T-cell engagers (BiTEs) are a novel class of fusion protein (55–60 kDa) consisting of two single-chain variable fragments (scFvs) derived from two distinct monoclonal antibodies specific to the surface antigen of tumor cells and the CD3ε subunit on all types of T cells." (PMID 34117317, 2021). "CD3E, the gene for novel membrane immune biomarker deeply affecting tumor purity, may help to evaluate the prognosis and develop individual immunotherapy strategies for LGG patients." (PMID 34557404, 2021). "Interestingly, both immune cell and tumor cell in the ROIs, low abundance of CD3E and IFNγ, plus IFNγ signature genes were observed." (PMID 33228231, 2020). "It is interesting that ATX, LPAR1, and LPAR5 are higher in the immune-high tumor (Cd14-, Cd68-, Cd164-, and Cd3E-high) group, but LPAR2.3 are higher in the immune-low group, suggesting the complex regulatory roles of the ATX–LPA axis in the tumor–immune system interaction." (PMID 31658655, 2019). "Over time, more Ly6G+ TANs and CD3ε+ TILs were found within the primary tumor mass." (PMID 31921184, 2019). "One rule of thumb, which may or may not bear out with time, is to have at least a ten-fold higher affinity to the tumor antigen than to the CD3ε." (PMID 31544847, 2019).
tumor (continued). "In marked contrast, in the Py230-based primary tumors, F4/80+ macrophages remained the predominant immune cell type (34%) at 6 w p.i., although closely followed in numbers by Ly6G+ neutrophils (16%) and CD3ε+ T-cells (24%), together approximating 75% of the primary tumor immunophenotype." (PMID 31921184, 2019). "Considering that the anti-CD20 × CD3ε 2:1 TCB format appears to be more potent than various 1:1 anti-CD20 × CD3ε formats, it might be interesting to see how other multiple-tumor-target-binding × single CD3ε binding formats might behave." (PMID 31544847, 2019). "The anti-CD3ε antibody UCHT1 enhanced the in vitro tumor killing activity of human γδ T cells by an unknown molecular mechanism." (PMID 30038626, 2018). "CD3ε contains endocytosis determinants that may contribute to the up- and downregulation of CD3ε on T cells and recent studies have provided evidence that CD3ε expression can be downregulated by tumor-educated tolerogenic DC and possibly by HIV." (PMID 29770136, 2018). "We also quantified the levels of tumor infiltrating T cells by CD3e immunohistochemistry." (PMID 24806510, 2014). "In addition, large numbers of lymphocytes that were immunoreactive for CD25 were observed within the tumor using confocal microscopy and flow cytometry (CD3ε+ CD25+ CD45+)." (PMID 18431473, 2008). "However, multipotent CD11b+/Lyve-1+/Ter-119+/CD3e+ progenitors detected in BM appeared to split into a predominant myeloid-lymphatic fraction and minor subsets expressing erythroid and T-cell markers upon establishing tumor residence." (PMID 38640116, 2024). "Additionally, we performed correlation analysis to corroborate the relationship between tumor infiltrated immune cells and the expression of the seven key hub genes (CTLA4, PRF1, LCK, CD3E, CD247, ZAP70, and LCP2) in ARID1A-PIK3CA mutational co-occurrence tumors." (PMID 38017109, 2023). "Moreover, the dual targeting CD19/CD3ε + TAG‐72/CD3δ or CD19/CD3ε + TAG‐72/CD3γ FP T cells killed TAG‐72hi CD19lo tumor cells, while the CD19/CD3ε single targeting FP T cells could not eradicate CD19lo cells." (PMID 38023726, 2023). "A decrease in surface CD3ε was also noted in cancer patients—both in tumour-infiltrating lymphocytes and peripheral blood T lymphocytes—in-vitro studies suggest that this may possibly be mediated by tumour-derived microvesicles." (PMID 35683597, 2022). "In EC, CD3E gene may be involved in the PD-1/PD-L1-mediated tumor immune escape process." (PMID 34124265, 2021). "Similarly, Gene Ontology enrichment analysis performed on transcripts upregulated in tumor samples with high CD3E expression revealed an overrepresentation in genes controlling TCR signaling, T-cell activation, co-stimulation, and cell adhesion molecules signaling." (PMID 33239635, 2020). "However, the increased CAR T‐cell abundance may also reflect an increase in CAR T‐cell homing and infiltration as CD3ε+ lymphocytes accumulated within the tumour and at the tumour/stromal interface at 10 days post‐adoptive transfer (Fig EV3B)." (PMID 31803974, 2020). "CD3E and PSMB9 were involved in the processes of antigen processing and presentation, and further enhances the anti-tumor immunity mediated by T lymphocytes." (PMID 40424327, 2025). "The extracellular domain of ITPRIPL1 directly binds to the CD3ε extracellular domain, inhibiting TCR‐CD3 signaling and hindering the initial activation of T cells, thus promoting tumor immune escape and progression." (PMID 40528483, 2025). "Upon internalization into tumor cells, TAK-280 initially binds to B7-H3 and, subsequently, within the protease-rich tumor microenvironment, engages with CD3ε." (PMID 40519928, 2025). "Tumor cells were identified using EPCAM, KRT18, and AFP as markers, while T/NK cells were identified by using the markers CD3D, CD3E, and GZMA." (PMID 40740783, 2025).
tumor (continued). "In the PD group, CD3e cells (0.18), CD8 T cells (0.22), and macrophages (0.35) within tumour regions showed the highest isPLA positivity, suggesting a potentially greater immune-suppressive capacity of the tumour microenvironment in these patients." (PMID 39939997, 2025). "Our approach in this study was to combine DARPins with high affinity and specificity toward CD3ε and HLA/TAA complexes, thus creating TCEs that can recruit, activate, and redirect CD8+ T cells to efficiently eliminate tumor cells." (PMID 41321628, 2025). "Based on the result derived from GEPIA, the expression of genes, including Cd3e, Cd274 (PDL-1), Wt1, Fate, Gbp2, and Cybb were significantly upregulated in the GBM tumor compared to the normal brain." (PMID 41282050, 2025). "Immunophenotyping of matched pre- and post-ICI samples demonstrated significant decreases in intratumoral lymphocytes, CD3e+ and CD8a+ T cells, and PD-L1–PD1 engagement, as well as increased distance between tumor cells and CD8+PD-1+ T cells." (PMID 38207230, 2024). "Note that in 4T1 and B16F10 tumor models, the relative abundance of FoxP3+ cells is higher than that of CD4+ and CD3ε+ cells in most runs." (PMID 38605049, 2024). "There was also a significant decrease in CD3e+PD-1+, CD8a+PD-1+, and CD4+PD-1+ T cells, as well as CD45+ cells in post- versus pre-ICI tumor samples (P < .05)." (PMID 38207230, 2024). "Through univariate Cox regression analysis, nine genes, including 3 oncogenes (HTR3C, CRHR2 and AGTR1), 6 tumor suppressor genes (CD8A, CD3E, SERPIND1, CXCR6, BMX and CD247) were proved to be correlated with the overall survival of EC patients." (PMID 38355782, 2024). "This approach relies on the recognition of tumor cell surface antigens and simultaneous binding to the CD3 epsilon chain (CD3ε) within the TCR complex." (PMID 39321199, 2024). "We generated tumor-educated, antigen-specific T cells and compared the effector T cell functionality effects on PDAC cells between tumor-educated and anti-Cd3e/Cd28-activated T cells." (PMID 38654067, 2024). "The custom mouse panel was designed to detect T cell biomarkers CD3ε, CD4, CD8α and FoxP3 and was evaluated on murine tumor specimens with varying levels of T cell infiltration." (PMID 38605049, 2024). "Note that with local thresholding, the MLE for CD3ε and CD4 are relatively consistent at ~ 75% in both CT26 and 4T1 tumor models." (PMID 38605049, 2024). "Second, an immune-related gene prognostic signature were established via regression analysis, including 2 oncogenic genes (AGTR1, HTR3C) and 2 tumor suppressor genes (SERPIND1 and CD3E)." (PMID 38355782, 2024). "We chose antibody clones that showed appropriate regional (e.g., splenic white pulp) and subcellular localization (e.g., cell membrane for CD3ε, CD4 and CD8α and nucleus for FoxP3) in spleen and tumor tissue." (PMID 38605049, 2024). "For example, according to a recent study, a platelet protein, TLT-1 was found to recognize the specific CD3ε region of CD8+ T cells, impeding the anti-tumor function of CD8+ T cells by regulating the NF-κB pathway." (PMID 37889543, 2023). "We observed similar tumor suppression up to 25 days, with TAG‐72 CAR‐T cells displaying a prolonged anti‐tumor response compared to TAG‐72/CD3ε FP T cells." (PMID 38023726, 2023). "As with the deletion of PTPN2 in T cells, we found that the systemic administration of Compound 182 and the repression of AT3-OVA tumor growth also increased p-STAT-1 staining within the tumor, as well as the abundance of CD3ε+ T cells." (PMID 37500611, 2023). "Both TAG‐72 CAR‐T cells and TAG‐72/CD3ε FP T cells displayed in vivo anti‐tumor activity as compared to the NT group, with TAG‐72 CAR‐T cells displaying a prolonged anti‐tumor response compared to TAG‐72/CD3ε FP T cells." (PMID 38023726, 2023). "IHC staining showed stronger expression of CD3D, CD3E, CXCR3 and IL2RG in tumor tissue compared to normal tissue." (PMID 37509334, 2023).
tumor (continued). "Most immune cell-engaging bispecific antibodies act by binding the CD3ε subunit on T-cells and a TAA on the tumor cell to form a cytolytic synapse." (PMID 37754534, 2023). "Our anti-PDL1-BiTE comprises of VL and VH chains of anti-CD3 monoclonal antibody (mAb) linked to the VL and VH chains of anti-PDL1 mAb, which simultaneously bind to the CD3ε subunit on T cells and PDL1 on tumor cells." (PMID 39282109, 2023). "CD3ε FP T cells were predominantly CD8+ effector memory T cells, and exhibited anti‐tumor activity in vitro and in vivo." (PMID 38023726, 2023). "CTP hampered tumor development and enhanced the ratio of CD3e−NK1.1+ cells by 113.0% and CD3e+CD28+ cells by 84.7% in the peripheral blood of ApcMin/+ mice." (PMID 35662701, 2022). "These included genes consistent with pro-inflammatory immune responses (CD27, CD28, CD3e, CD8a, ICOS, ICOSLG, Pax5, TBX, GATA3, HLA-A, TNFSF14, GPR146), but also immune suppressive influences in the tumor immune microenvironment (CTLA-4, FoxP3, PD-1)." (PMID 36698398, 2022). "The intracellular signaling domain of CD3ε contains an immunoreceptor tyrosine-based activation motif (ITAM) domain, which can activate and evoke T cells to lyse tumor cells in the presence of BiTEs." (PMID 36230871, 2022). "Unexpectedly, the C8 population of cancer cells expressed T-cell markers (CD3D, CD3E, CD7), which is recognized as a dual identity of T cells and tumor cells involved in the role of the TME." (PMID 36451812, 2022). "The tissue was stained with fluorescent markers for PanCK (tumor and epithelial cells), CD45 (immune cells), CD3e (T cells) and DNA." (PMID 35046414, 2022). "To better understand the transcriptional heterogeneity in tumor-infiltrating T lymphocytes (TILs), we identified T- cell clusters that expressed known T- cell markers (CD3D and CD3E)." (PMID 36569924, 2022). "Some well-known marker genes were used to identify cell types, such as EPCAM and KRT19 for tumor cell, COL1A1 and ACTA2 for CAF, CD3D and CD3E for T cell, and CD68 and CD14 for macrophage." (PMID 36499343, 2022). "The main cell clusters included T cells (CD3E and CD3D), B cells (CD19), natural killer cells (NCAM1, FCGR3A and KLRD1), myeloid cells (CD86 and CD163) and tumor cells (EPCAM, KRT8 and KRT18)." (PMID 36497182, 2022). "We next explored the association of the expression at an individual transcriptomic level of CD2, CD3D, CD3E, and CXRC6 with the presence of tumor-infiltrating immune cell populations." (PMID 34692491, 2021). "The expression levels of CCL5, CD3E, and LCK were lower in tumor tissues samples than those in adjacent non-tumor tissue samples, which is consistent with the results of transcriptomics." (PMID 34218795, 2021). "T and tumor cells were identified by the expression of classic cell type markers, including PTPRC, CD3G, CD3E, TRBC1, and CD8B for T cells and MAGEA 4 for MEL-526 cells." (PMID 33754038, 2021). "The ionic interaction between LCK and CD3E controls the TCR phosphorylation, which is considered as the initial step in T-cell signaling to trigger adaptive immunity against tumor cells." (PMID 35004669, 2021). "The results showed that the expression of CCR5, CD3E, CD4, and HLA-DRB1 mRNAs in tumor tissues was significantly higher than that of normal tissues adjacent to the tumor." (PMID 34490269, 2021). "Compared with normal control tissues, the expression level of CD3D and CD2 in tumor tissues were not significantly different, while the expression levels of CD3E, CD3G, CCL5, CXCR6 and LCK in tumor tissues were lower than those in normal tissues (P < 0.05)." (PMID 34218795, 2021). "Among these, 4 genes (CD8A, CD3E, CCL4 and ITGAL) were reported to have close relationship with tumor immune microenvironment and to be involved in various pathological processes of EC35–37." (PMID 34131259, 2021).